BRAF (B-Raf proto-oncogene, serine/threonine kinase)
Diseases named in the same sentence as BRAF in open-access papers (continued):
Sharing a sentence is not in itself a finding about the gene and the disease.
melanoma (continued). "Finally, we were interested whether this mechanism applies for BRAF mutated cancer cell lines as well and therefore analyzed MIG-6 expression in previously published microarray data, obtained within the BRAF V600E mutated melanoma cell line A375." (PMID 26065894, 2015). "In order to determine whether the MEK1T55delinsRT mutation conferred resistance to BRAF inhibition in vivo also, A375 melanoma cells, after they had been retrovirally transduced with cDNAs encoding GFP, MEK1WT or MEK1T55delinsRT, were injected subcutaneously into immune-deficient mice." (PMID 26105199, 2015). "Furthermore this case confirms the fact that malignant melanoma has the potential to cause miliary brain metastasis and raises the question if there might be an association between BRAF status and miliary pattern of metastasis." (PMID 26187589, 2015). "Whether BRAF inhibitors benefit patients with a kinase-activated BRAF mutation located outside codon 600 remains less clear, although a partial response to vemurafenib has been reported in a melanoma patient with a p.L597R mutation." (PMID 26498038, 2015). "However, resistance in BRAF-mutated melanoma appears to develop at 6 to 7 months (Long, Stroyakovskiy, & Gogas, 2014), so pembrolizumab may be an option upon recurrence." (PMID 26557410, 2015). "However, treatment options remain limited for the patients that lack mutations in the five most commonly mutated melanoma genes (BRAF, NRAS, KIT, GNAQ and GNA11) and the prognosis of such patients is particularly pool with a median overall survival of less than 1 year." (PMID 26424083, 2015). "Although inhibitors of oncogenic BRAF generally exert a temporary therapeutic efficacy in patients with metastatic BRAF-mutated melanoma, recent evidences seem to indicate that subsets of such cases may present a long-term response to single-agent BRAF inhibition." (PMID 26322273, 2015). "Furthermore, it has been shown that in melanoma, BRAF mutations induce autophagy." (PMID 25741318, 2015). "Furthermore, mutation or overexpression of CDK4, combined with amplification of cyclin D1, has been implicated in resistance to BRAF inhibition in V600E-mutated melanoma cells, and amplification of cyclin D1 is detected in ~17% of BRAF V600E-mutated human metastatic melanomas." (PMID 26201960, 2015). "Thus, we support that the use of additional and more sensitive techniques may improve the ability to detect BRAF mutations in melanoma patients." (PMID 26690267, 2015). "For the histology‐agnostic Type IB trial, the assumption that a molecular aberration behaves identically across histologies may not be true, exemplified by BRAF mutation and differences in clinical benefit in melanoma and colorectal cancer with inhibitory BRAF monotherapy." (PMID 25557400, 2015). "The combination of selumetinib and dacarbazine has demonstrated clinical activity in a phase II trial, with significant improvements in PFS observed in patients with BRAF mutation-positive advanced cutaneous or unknown melanoma receiving the combination versus dacarbazine alone." (PMID 26059332, 2015). "Interestingly, a recent study has suggested that PTEN loss may contribute to BRAF inhibitor resistance in melanoma." (PMID 24830350, 2014). "Additionally, the use of dabrafenib in non–BRAF V600E-mutated melanoma continues to beinvestigated." (PMID 25089220, 2014). "Loss of PTEN may promote melanoma development, possibly as a cooperating mutation with BRAF V600E." (PMID 24830350, 2014). "The fact that the BRAF mutation was found to be associated with epithelioid cells, that is, cells that potentially have the greatest metastatic capability, might be important to better understand the biologically mechanism that underlie mutant BRAF and melanoma." (PMID 25526463, 2014).
melanoma (continued). "In their present set-up, the cobas® 4800 BRAF V600 test as well as the therascreen® BRAF Pyro Kit are therefore not sufficient for the European approval of vemurafenib because there is a therapeutic option for melanoma patients with any mutation in codon 600 of the BRAF gene." (PMID 24410877, 2014). "In melanoma, the elevated intracellular concentration of CyclinD1, related to the amplification of the gene locus at chromosomal level, has been implicated into the resistance to both BRAF and MEK inhibitors since it promotes a MAPK-independent cell proliferation." (PMID 24885594, 2014). "Melanoma cells are addicted to oncogene-driven energy production which can be mediated by somatic BRAF mutations, our findings indicate that non transformed skin cells already have a deregulated metabolic profiling which may be necessary for the skin cancer initiation." (PMID 24742402, 2014). "Mutations in BRAF lead to constitutive activation of downstream signaling of the RAS-RAF-MEK-ERK (mitogen-activated protein kinase) signal transduction pathway in 40-60% of cutaneous melanoma with substitution of glutamic acid for valine at codon 600 in 90% of the BRAF-mutated melanoma." (PMID 24499550, 2013). "Importantly, similar results were obtained when xenografts were generated by wild type-BRAF melanospheres indicating that this strategy might constitute a potentially exploitable therapeutic approach both for mutated-BRAF and wild type-BRAF melanoma patients." (PMID 24238212, 2013). "As it has been previously shown that the BRAF V600E mutation conveys sensitivity of melanoma cells to BRAF and MEK inhibitors and the phenothiazine compounds, we next addressed whether the presence of a BRAF or NRAS mutation conferred sensitivity to dinaciclib." (PMID 23527225, 2013). "Interestingly, copy-number gains of the BRAF gene have been proposed as an alternative mechanism of activation in both melanoma and glioma, as well as being a cause of resistance towards BRAF inhibitor treatment of advanced melanoma." (PMID 23673558, 2013). "Indeed, the loss of some negative feedback regulators might contribute to tumor progression, but might also be expressed at considerably higher levels in oncogene-mutant tumors as observed in BRAF-mutated melanomas." (PMID 23889749, 2013). "Therefore it is unknown if BRAF or NRAS mutations play any role in the progression of a nevus into a melanoma." (PMID 23861977, 2013). "Therefore, we propose that initial co-treatment of melanoma patients bearing BRAF mutations with an anti-ErbB3 antibody could be a powerful strategy to enhance clinical efficacy of BRAF and MEK inhibitors." (PMID 23890105, 2013). "BRAF mutation predicts shorter OS in stage IV melanoma, which is consistent with clinical outcomes of tumor regression upon Vemurafenib administration in advanced melanoma patients; inhibition of a marker that is directly associated with poor prognosis results in prolonged survival." (PMID 23951556, 2013). "We posit that, direct or up/down-stream “pharmacologic normalization” of the R87P-p16 mutation, individually and together with BRAF intervention, may enable more effective strategies to delay or even prevent FM, including the occurrence of melanoma in individuals who are otherwise at risk." (PMID 23371019, 2013). "Finally, as MEK inhibition was highly cytotoxic for differentiated melanoma cells it is likely to hypothesize a combined treatment for wild type BRAF tumors with MEK inhibitors in association with differentiating agents." (PMID 24238212, 2013). "Also, diagnosis of malignant melanoma can be made if a BRAF mutation is found." (PMID 24274261, 2013). "Of the over 40 BRAF activating mutations identified, the BRAFV600E mutation is the most common, and accounts for 92% of BRAF mutations in sporadic melanomas and 82% of benign nevi, implying that it might be involved in the progression from a benign to a cancerous state." (PMID 23372575, 2012).
melanoma (continued). "Despite indications that inhibitors of mutated BRAF may represent an effective therapeutic approach in melanoma brain metastases, our patient in this case showed responsiveness on visceral sites but dramatic disease progression to the leptomeninges during therapy with BRAFi." (PMID 22594466, 2012). "However, it is still possible that the benign nevi with mutated BRAF can escape the oncogene-induced senescence and become melanomas, which might explain the high percentage of this mutation in sporadic melanoma." (PMID 23372575, 2012). "In an attempt to identify genes which could potentially confer resistance to B-Raf inhibitors, one group expressed a panel of approximately 600 kinase-related open reading frames in normally B-Raf inhibitor-sensitive A375 melanoma cells, which contain the BRAF V600E mutation." (PMID 23085539, 2012). "Thus, it is possible that many melanomas labelled as wild-type BRAF by direct sequencing may carry mutations, albeit at low levels below the sensitivity of the method." (PMID 21224857, 2011). "WGA also offers the opportunity to uncover previously unknown (perhaps patient-specific) mutations in melanoma genomes and to explore whether particular profiles of mutations or polymorphisms may be predictive of benefit from a particular therapy (i.e., BRAF inhibitors, HD IL-2)." (PMID 22175026, 2011). "Here, we tested whether similar heterogeneity of BRAF mutations exists in primary melanomas." (PMID 21224857, 2011). "Furthermore, it seems envisagable that the same mechanism could also be active in other tumors with high BRAF mutation frequency, such as melanomas." (PMID 20877637, 2010). "This is possibly because NRAS-mutated melanoma may bypass BRAF and signal through CRAF." (PMID 19949544, 2009). "However, since also benign melanocytic nevi as classical melanoma precursor lesions showed a high percentage of activating BRAF mutations, further molecular mechanisms might contribute to primary tumor development." (PMID 19642975, 2009). "However, it remains to be determined whether such a feedback mechanism impairs clinical response to sorafenib monotherapy in melanomas with V600E BRAF mutations." (PMID 16880785, 2006). "Since little is known about the clinical implications of activating BRAF mutations in melanoma tumors, we examined whether the melanoma tumors harboring BRAF mutations in this cohort showed different clinical or biological features compared to the melanoma tumors without mutations." (PMID 15613230, 2004). "Preclinical work (mEL 3) showed an effect of the MEK1/2 inhibitor trametinib in AGK::BRAF-positive melanoma models." (PMID 41554728, 2026). "Collectively, these findings demonstrate that ONC disrupts redox homeostasis, mitochondrial function, and survival signaling in melanoma cells, exerting particularly potent effects in BRAF inhibitor-resistant populations." (PMID 41751773, 2026). "For advanced BRAF‐mutant melanoma, targeted therapies—such as the BRAF inhibitors dabrafenib and vemurafenib—have become standard treatment." (PMID 41492362, 2026). "Subsequent studies have shown that combination therapy of BRAF and MEK inhibitors provides better outcomes than single agent of BRAF inhibitor for BRAFmut melanoma, becoming the current standard scheme." (PMID 41492362, 2026). "BRAF inhibitors (BRAFi) have transformed the treatment of BRAF mutant melanoma, but inherent and acquired resistance remains a major barrier to curative outcomes." (PMID 41807883, 2026). "The FDA approval of targeted therapies for BRAF-mutant melanoma greatly increased overall survival in considerable number of patients." (PMID 41982244, 2026). "Combined inhibition of CDK12 and MAPK signaling produces synthetic lethality in melanoma cell lines and murine models, highlighting the potential of dual pathway targeting to overcome resistance to BRAF and MEK inhibitors." (PMID 41491919, 2026).
melanoma (continued). "BRAF was the most frequently altered driver gene, present in 7 nevi and 10 melanomas, consistently through the canonical V600E hotspot." (PMID 41516405, 2026). "The most frequent pathogenic molecular alteration in these melanomas were found in NRAS (25%) and BRAF (25%)." (PMID 41595691, 2026). "Resistance to BRAF/MAPK inhibitors is a significant challenge in melanoma treatment, driven by adaptive and acquired mechanisms allowing tumor cells to evade therapy." (PMID 41708984, 2026). "We retrospectively analyzed data from patients with resected stage III BRAF V600-mutant melanoma who received adjuvant therapy between June 2013 and December 2023 across three centers in China." (PMID 42039710, 2026). "About 50% of melanoma detect that valine replaces glutamate at codon 600 (V600E), leading to activation of BRAF protein kinase and downstream MAPK pathway." (PMID 41492362, 2026). "In the future, larger‐scale clinical trials are needed to better understand the potential benefits and limitations of these combination therapies in NRAS/BRAF‐mutant melanoma." (PMID 41492362, 2026). "While adjuvant immunotherapy and BRAF/MEK inhibitors improve the outcomes for BRAF V600-mutant stage III melanoma, comparisons of long-term survival and safety of these therapeutic modalities are currently lacking in Chinese patients." (PMID 42039710, 2026). "Overall and progression-free survival (OS, PFS) following target therapy with BRAF/MEK inhibitors were comparable to V600E/K mutant melanoma (HR = 0.85 and 0.89, p > 0.1)." (PMID 42003243, 2026). "The combination of hydroxychloroquine, dabrafenib, and trametinib in the treatment of BRAF‐mutant melanoma was tested in another prospective Phase I/II trial (BAMM, NCT02257424)." (PMID 41492362, 2026). "Melanoma is the most aggressive skin malignant tumor, typically exhibiting a high mutation burden and potentially harboring mutations in NRAS, BRAF, or NF1." (PMID 41492362, 2026). "Recently, we reported that shRNA‐ or ND322‐mediated inhibition of MT1‐MMP synergized with BRAF inhibitor (BRAFi) leading to resensitization of resistant melanoma cells and tumours to the inhibitor." (PMID 41546170, 2026). "A 43-year-old woman with metastatic BRAF wild-type melanoma, in complete metabolic response on lenvatinib and pembrolizumab, presented with generalized edema, hypotension, thrombocytopenia, and marked erythroblastosis." (PMID 42187585, 2026). "Antitumor efficacy was evaluated in AML xenografts and A375 melanoma (AXL overexpression, BRAF V600E mutation)." (PMID 41958931, 2026). "Melanoma frequently develops resistance to BRAF/MEK-targeted therapy and immune checkpoint blockade (ICB), often through therapy-driven tumor state transitions that include immune exclusion, transcriptional plasticity, and microenvironmental remodeling." (PMID 41958557, 2026). "Combination studies were performed on BRAF mutated melanoma cells treated with DT2216 and Dabrafenib/Trametinib or on wild type melanoma cells treated with DT2216 and Trametinib or S63845." (PMID 41501884, 2026). "Canonical MAPK pathway mutations were common: BRAF V600E and NRAS Q61 variants were detected in many nevi and melanomas and were shared between lesions in 8 of 15 patients, providing direct evidence of clonal continuity." (PMID 41516405, 2026). "Based on these observations, a Phase IB trial of NCT02138292 investigated the digoxin and trametinib in advanced BRAF wild‐type melanoma including six patients with NRASmut melanoma." (PMID 41492362, 2026). "By contrast, D + T therapy achieved an intracranial response rate of 58% in patients with BRAF V600-mutant melanoma brain MTS, compared with 31% in patients treated with dabrafenib monotherapy." (PMID 41209431, 2026). "In preclinical models and in patients with BRAF‐mutant melanoma, treatment with BRAF inhibitors (BRAFi) increased intratumoral CD4+ and CD8+ lymphocytes." (PMID 41514118, 2026).
melanoma (continued). "When diagnosed, patients with NRAS or BRAF mutations tend to have a higher AJCC stage, particularly Stage III, compared with wild‐type melanoma." (PMID 41492362, 2026). "The age at diagnosis of NRASmut melanoma is typically around 60–70 years, which is higher than melanoma with BRAF mutations or NRAS/BRAF wild‐type." (PMID 41492362, 2026). "Subsequently, we explored current and potential treatment approaches for melanoma, primarily encompassing BRAF inhibitors, MEK inhibitors, and immunotherapy, with a particular focus on their clinical relevance of development." (PMID 41492362, 2026). "In a study of adjuvant PD‐1 inhibitor therapy for Stage III melanoma, there were 23 patients (20%) that harbored BRAF mutation, 21 patients (18.3%) harbored NRAS mutation, and 59 patients (51.3%) with BRAF/NRAS wild‐type." (PMID 41492362, 2026). "NRASQ61‐mutated melanoma relies on glucose metabolism, and glucose deprivation promotes the conversion of CRAF to BRAF, leading to BRAF‐mediated phosphorylation of PFKFB2/PFKFB3, key glycolytic enzymes that mediate the response to metabolic stress." (PMID 41492362, 2026). "Several Phase II/III studies tested the efficacy of immune checkpoint inhibitors (ICIs) combined with BRAF/MEK inhibitors for BRAFmut melanoma and the results were desirable." (PMID 41492362, 2026). "Previous studies have demonstrated that MAPK pathway play a dominate role in NRAS/BRAF mutant melanoma compared with the PI3K pathway." (PMID 41492362, 2026). "The limited FDA-approved options for BRAF V600E-positive thyroid cancer compared to melanoma underscore the need for further research to optimize and expand treatment strategies." (PMID 41727688, 2026). "Double‐blind multicenter Phase II trial (DOC‐MEK, NCT01256359) randomized (1:1) patients with wild‐type BRAF melanoma to docetaxel with selumetinib or placebo." (PMID 41492362, 2026). "This study provides promising treatment opportunities for patients with non-BRAF-mutant melanomas, or those who relapse following belvarafenib and cobimetinib combination therapy." (PMID 42091854, 2026). "Trametinib, the first US FDA‐approved MEK inhibitor for advanced melanoma, has achieved great success in combination with BRAF inhibitors for BRAFmut melanoma." (PMID 41492362, 2026). "tested the hydroxychloroquine, dabrafenib, and trametinib for BRAF‐mutant melanoma patients previously treated with BRAF/MEK inhibitors and ICIs in the Phase II study." (PMID 41492362, 2026). "Nevi most often harbored canonical MAPK-pathway mutations in BRAF and NRAS, as well as in GRIN2A, while melanomas, along with BRAF and NRAS, frequently carried additional driver alterations in ARID1A, ARID2, CDKN2A, and PTEN." (PMID 41516405, 2026). "NRASmut melanoma patients had a response rate more than twice that of BRAF‐mutant or NRAS/BRAF wild‐type patients (47 vs." (PMID 41492362, 2026). "In BRAF-mutant melanoma cells, an interaction between DDR1 and intβ1, regulated by Kindlin-3, has been observed." (PMID 41492134, 2026). "BRAF inhibitors such as vemurafenib (PLX4032) and dabrafenib have demonstrated remarkable clinical activity in melanoma patients with BRAFV600 mutations." (PMID 41492362, 2026). "BRAF V600 inhibitors are clinically approved for the treatment of BRAFV600-mutant melanoma in combination with a MEK inhibitor, but are ineffective in other melanoma subtypes." (PMID 42091854, 2026). "These discoveries resulted in the FDA’s approval of vemurafenib in 2011 and dabrafenib in 2013, as single agents, for the treatment of metastatic BRAF V600E-mutant melanoma." (PMID 41514664, 2026). "For instance, mutations in genes such as BRAF and NRAS are common in both canine and human melanomas, making canine melanoma a valuable model for studying melanoma-specific immunotherapies." (PMID 40386779, 2025). "For example, in BRAF-mutant melanoma treated with BRAF/MEK inhibitors, a baseline MTV above approximately 56 cm3 predicted worse progression-free survival (PFS)." (PMID 41008677, 2025).